CD4 (CD4 molecule)
Diseases named in the same sentence as CD4 in open-access papers (continued):
Sharing a sentence is not in itself a finding about the gene and the disease.
toxoplasmosis (continued). "Our findings demonstrate quantitative and qualitative features of an effective Toxoplasma-specific CD4+ T cell response that should be considered in testing next-generation vaccines against toxoplasmosis." (PMID 37766162, 2023). "CD4+ T cells are critical for resistance to T. gondii infection, and toxoplasmosis often leads to alterations in the number and function of CD4+ T cells." (PMID 37077528, 2023). "Previous studies have shown that the CD4+ T cell-stimulating peptide AS15 confers significant protection against toxoplasmosis in C57BL/6 mice." (PMID 37766162, 2023). "Previous studies have revealed that CD4+ T lymphocytes are essential in mediating immunity against toxoplasmosis, while CD8+ T lymphocytes play an important role in the cytotoxic effect." (PMID 34512659, 2021). "Significant risk factors for toxoplasmosis in HIV+ patients included the consumption of raw/undercooked meat, frequent contact with soil, a low CD4+ T lymphocyte number (<200 cells per μL) and age." (PMID 34683355, 2021). "Although a low CD4+ T cell count (<200 per μL) is a risk factor for opportunistic infections in HIV+ people, severe toxoplasmosis occurs in people with advanced AIDS, when CD8 T cell deficiency allows a reactivation of latent T. gondii infection." (PMID 34683355, 2021). "During both periods, median treatment/turnaround times were similar for; when CD4 count results were received, Toxoplasmosis and PCP treatments were started after initial diagnosis, and when antibiotics were given to patients after prescription." (PMID 33028245, 2020). "Our current studies reveal that despite this return of CD8α DCs, CD4 T cells remain the dominant subset contributing to IFN-γ levels needed to control toxoplasmosis." (PMID 32669460, 2020). "To definitively assess if IL2C-mediated expansion of IL-18-responsive IFN-γ-secreting non-CD4 cell subsets can prevent lethal toxoplasmosis in mice, we used the well-established oral inoculation model with T. gondii ME49 bradyzoite-containing brain cysts." (PMID 32753607, 2020). "Overall, the depleted CD4 population during the late stages of HIV infection compromises the CD8 T cell immunity against the chronic (latent) toxoplasmosis leading to reactivation of the infection." (PMID 31119107, 2019). "The occurrence of both IgM and IgG antibodies together with the severe drop in CD4 T cells and the presence of striking generalized lymphadenopathy in four of presented patients indicated the reactivation (relapse) of toxoplasmosis." (PMID 31690039, 2019). "In general, the clinical course of toxoplasmosis in HIV-positive patients significantly depends on the CD4 T lymphocyte count." (PMID 31690039, 2019). "Although depleted CD4 numbers in HIV patients lead to increased susceptibility to TE, most cases of toxoplasmosis in HIV patients occur during the late stage of HIV infection (advanced AIDS), when a deficiency in CD8 T cells is also evident." (PMID 31119107, 2019). "Cotrimoxazole prophylaxis for toxoplasmosis and pneumocystis in Cameroon is commenced at CD4+ cell counts below 200 cells/mm3." (PMID 29970017, 2018). "The CD4 T cells are an essential source of cytokines, which are important mediators of protective immunity against acute Toxoplasmosis." (PMID 29163509, 2017). "Toxoplasmosis was suspected on the basis of focal palsies in patients with low CD4 count, but rarely confirmed through image techniques such as CT scan, which is not available in Ifakara." (PMID 28719610, 2017). "In conclusion, we described that toxoplasmosis imprints intracellular signals that activate CD4+ and CD8+ T cells to produce IFN-γ." (PMID 28439500, 2017). "CD4 levels in HIV-positive patients with seropositive toxoplasmosis (range, 3 to 273 CD4 cells/μl of blood) were lower than seronegative patients (range, 345 to 463 CD4 cells/μl of blood)." (PMID 27083153, 2016).
toxoplasmosis (continued). "CD4 T cells are critical in the immune defense against toxoplasmosis in HIV infection and the reactivation of T. gondii infection is associated with the decline of this T cell subset." (PMID 26247013, 2015). "Consistent with a role for these innate cells in limiting microbiota-specific responses during toxoplasmosis, an increased frequency of CD4+ T cells in Ahr-/- mice produced IFN-γ following stimulation with crude commensal antigen preparations." (PMID 26010337, 2015). "Patients based age category, availability of OI prophylaxis, baseline CD4 count and presence of toxoplasmosis, WHO staging on treatment, and TB screened status were some of the variables that showed significance in Log rank test." (PMID 25452834, 2014). "In murine models, CD4+ T cells were crucial regulators of the immune response during resistance against toxoplasmosis, while in humans CD4+ displayed cytotoxic activity against T. gondii infected cells." (PMID 25201636, 2014). "Although several studies have demonstrated the importance of CD4+ T-cells in infection control, the production of proinflammatory cytokines, mainly by CD4+ T cells, is related to the morbidity of toxoplasmosis." (PMID 25328286, 2014). "Diffuse toxoplasmosis encephalitis should be considered in patients with anti-T gondii immunoglobulin G (IgG) antibodies and CD4 T-cell counts of <100/μL who present with unexplained neurologic disease." (PMID 24447375, 2014). "In a mouse model of toxoplasmosis, in addition to inflammatory monocytes and neutrophils, CD4+ and CD8+ T lymphocytes where also important source of MMP-8 and MMP-10." (PMID 25393535, 2014). "Toxoplasmosis can be a life-threatening disease when it occurs in patients with HIV infection with decreased CD4 positive lymphocytes." (PMID 20701779, 2010). "Seven of the HIV-infected patients with toxoplasmosis had a low CD4+/CD8+ T cell ratio." (PMID 40709328, 2025). "Since both CD4+ and CD8+ cells are essential in the humoral response to the presence of the parasite, the depletion of both cell types results in increased susceptibility to toxoplasmosis." (PMID 36678458, 2023). "Moreover, host response to toxoplasmosis acute infection is characterized by a strong inflammatory activation mediated by the Th17 CD4 lymphocytes producing IL-1737." (PMID 33139781, 2020). "These are very important studies and data obtained from these experiments will enable the target of co-stimulatory molecules needed to reverse CD4 T cell dysfunctionality which, in case of Toxoplasmosis and other chronic infections, is important for the maintenance of CD8 T cell immune response." (PMID 31119107, 2019). "Similarly, the emergence of severe toxoplasmosis in patients infected with HIV is concomitant with a decline in CD4 T cell numbers." (PMID 31119107, 2019). "Moreover, our results also clearly suggest a relationship between the number of CD4 T lymphocytes and toxoplasmosis reactivation." (PMID 31690039, 2019). "Moreover, CD4+ T cells constitute an important component of the immune response to T. gondii, and AS15 is a CD4+ T cell-stimulating peptide that can confer protection against toxoplasmosis." (PMID 30984177, 2019). "Although CD4 T cells play a key role in the immunity against T. gondii as important producer of IFN-γ, CD8 T cell and NK cell deficiencies were previously demonstrated to contribute to toxoplasmosis reactivation." (PMID 26247013, 2015). "In the eye, infiltrates of CD4+ CD25+ T cells are specifically found in the retina of patients with recently acquired toxoplasmosis indicating that recently orally ingested parasite leads to the presence of these immune-regulatory cells in their infected retinas." (PMID 24225023, 2013). "Furthermore, CD4 value was lower in the toxoplasmosis group compared to the control." (PMID 38950027, 2024).
toxoplasmosis (continued). "Furthermore, the tachyzoite-induced NETs promote neutrophil and CD4 T cell recruitment as well as Th1 and Th17 cytokine release and might have important implications for the outcome of human toxoplasmosis." (PMID 34607465, 2021). "Toxoplasmosis: Tests for toxoplasmosis were conducted on pregnant women or women enrolled in programmes for in vitro fertilisation, patients with lymphadenitis, patients with vague febrile illness, patients with inflammation of the eye and immunocompromised patients with low CD4 cell counts." (PMID 28903890, 2018). "Patients on antiretroviral therapy can safely discontinue primary prophylaxis for toxoplasmosis if their HIV viral load is suppressed and their CD4 count remains above 200 cells/μL for at least three months." (PMID 41181720, 2025). "The severe clinical consequences of toxoplasmosis in HIV-1-infected subjects with severe immunosuppression, CD4 cell count <100 cells/mm3, requires the precise monitoring of the T. gondii infection markers." (PMID 35160090, 2022). "T cell-mediated immune defense is relevant to the control of toxoplasmosis, and CD8+ and CD4+ lymphocytes play a critical role during the adaptive immune response against T. gondii infection and reactivation." (PMID 30564214, 2018). "Currently, individual B, CD4+ T, CD8+ T cell epitopes have been able to induce partially protective immune responses against toxoplasmosis, and MAP vaccines are more likely to confer more robust protection." (PMID 29876322, 2018). "There are many fundamental questions about the mechanisms of antigen presentation that lead to the activation of CD4+ and CD8+ T cells during toxoplasmosis and multiple studies have addressed the ability of actively infected cells to present antigen." (PMID 24722202, 2014). "ELISPOT assesses CD4+ and CD8+ T cell responses to antigens, and facilitates the identification of T. gondii-specific IFN-γ producing memory T cells in patients with both toxoplasmosis and HIV." (PMID 40709328, 2025). "Previous studies have shown that during toxoplasmosis or trypanosomiasis the absence of IL-27 results in enhanced CD4+ T cell responses which contribute to increased accumulation of inflammatory monocytes." (PMID 39868131, 2025). "Although the exact prevalence of toxoplasmosis in South Africa is unknown, serological testing should be considered in PLWH (ARV naive) with CD4 cell counts less than 50 cells/μL." (PMID 40951615, 2025). "Owing to his compromised CD4 count, he contracted TB, CMV, and toxoplasmosis." (PMID 39104429, 2024). "Previous studies revealed that patients lacking CD4 and CD8 T cells are susceptible to toxoplasmosis and predisposed to toxoplasmas encephalitis in chronic infections." (PMID 39416787, 2024). "In the present study, a significant increase in CD4+ and CD8+ T lymphocytes compared with that in the control group suggested that TG_200 mRNA-LNP plays an important role in the induction of CD4+ and CD8+ T lymphocytes against toxoplasmosis." (PMID 37122740, 2023). "We demonstrate protection of HLA-A*11:01, HLA-A*02:01, and HLA-B*07:02 mice against toxoplasmosis by (i) this novel chimeric polypeptide, containing epitopes that elicit CD8+ T cells, CD4+ T helper cells, and IgG2b antibodies, and (ii) adjuvant activation of innate immune TLR4 and TLR5 pathways." (PMID 33046728, 2020). "Natural killer, CD4+ and CD8+ T cells all together will produce large quantities of IFN-γ to expedite the production of protective helper T-cell type 1 immunity against acute and reactivated toxoplasmosis." (PMID 33575600, 2020). "Toxoplasmosis, non-Hodgkin’s lymphoma and bacterial pneumonia were not consistently recorded before 2013; the prevalences among adults with first CD4 count <200 cells/mm3 in 2014 were 2.2%, 0.5% and 8.9%, respectively." (PMID 28719610, 2017). "Cerebral toxoplasmosis usually affects HIV-infected patients with CD4 count of less than 200 cells per cubic millimeters and not taking toxoplasmosis prophylaxis." (PMID 24073002, 2013).
toxoplasmosis (continued). "A significant difference was observed in the CD4+ T cell count between HIV-positive patients with and without toxoplasmosis." (PMID 40709328, 2025). "Although protection against toxoplasmosis in the immunocompetent C57BL/c mice is largely dependent on CD8 T cells, in the absence of NK cells and CD8 T cells, CD4 T cells become an essential source for IFN-γ." (PMID 32669460, 2020). "However, we enrolled a low number of patients with a CD4 count less than 100 and most of our patients receiving HAART without clinical manifestation of toxoplasmosis." (PMID 31531103, 2019).
encephalitis (89 papers, 2007 to 2026). An acute inflammatory process affecting the brain parenchyma. "Previous studies from our laboratory have reported that in an encephalitis model of infection, CD4 T cell dysfunction leads to CD8 T cell loss of function during the late stages of chronic infection." (PMID 36883950, 2023). "Tregs that recognize the immunodominant CD4+ T cell epitope are found in the brains of rJ2.2 strain of MHV-infected mice, where they inhibited pathogenic CD4+ T cell responses to ameliorate encephalitis severity." (PMID 38114497, 2023). "Participants who experienced the most severe symptoms, meningitis, and encephalitis exhibited a measurable loss of both Tn CD4 and CD8 T cells as compared to at least one other group." (PMID 35289071, 2022). "Adoptive transfer of MHV-specific Treg enhanced the survival rate of infected mice by reducing the frequencies of pathogenic CD4+ T cells and microglial responses in the brain in acute encephalitis." (PMID 32131483, 2020). "This dependence of CD8 bTRM differentiation on CD4 T cells was found to extend to encephalitis caused by vesicular stomatitis virus." (PMID 30372487, 2018). "This feature is of particular interest, since a study with knockout mice previously immunized and intracerebraly injected with a neurotropic strain of 17D virus has shown that specific CD4+ T cells are required to protect mice against lethal encephalitis caused by this virus." (PMID 24324734, 2013). "T cells may play a role in protection from encephalitis caused by flaviviruses; it has been demonstrated that the depletion of CD4+ and/or CD8+ lymphocytes leads to a decrease in the protection offered by an experimental vaccine expressing the dengue envelope protein in the context of the YF virus." (PMID 25875109, 2015). "CD8 + encephalitis is a rare and underdiagnosed condition that causes cognitive and behavioral changes in patients with HIV, even those with normal CD4 counts and those on antiretroviral therapy." (PMID 41409353, 2025). "First, we compared the frequencies of peripheral CD24hiCD38hi transitional B cells in CD19+B cells, CD24hiCD27+ B10 B cells in CD19+B cells, Tfh in CD4+T cells, and Tregs in CD4+T cells between anti-NMDAR encephalitis, NMOSD, IIH, and HC." (PMID 36781561, 2023). "Studies in rats with BoDV-1 encephalitis showed clinical improvement and reduction in CD4 and CD8 infiltration of the brain after intrathecal administration of the compound, although the virus concentration did not decrease." (PMID 36821024, 2023). "HIV-infected individuals carrying latent toxoplasma infection develop encephalitis, and it is believed that the reactivation occurs during the advanced stage of the disease when CD4 T cells are severely depleted." (PMID 36883950, 2023). "In another case of ICI-related encephalitis, the PD-1 receptor occupancy was total on CSF CD4 T cells, but only partial on peripherical CD4 T cells." (PMID 36605194, 2022). "Transfer of Y- and PS-specific CD4+ and CD8+ T cells was also effective in preventing signs of encephalitis, weight loss, and tissue injury upon TMUV Y infection, with Y-specific T cells being more effective than PS-specific T cells." (PMID 36016955, 2022). "Following infection with neurovirulent JHM strain of MHV, insufficient Treg responses with dominant virus-specific CD4+ responses correlated with acute fatal encephalitis of mice." (PMID 32131483, 2020). "Here we analyzed the T cell receptor repertoires of CD8+ and CD4+ T cells in a patient with “idiopathic” gamma‐aminobutyric‐acid‐A receptor (GABAA‐R) encephalitis by next‐generation sequencing and single‐cell analyses." (PMID 31943946, 2020). "A relationship between increased neuropathology and CD4 independence in an SHIV-induced encephalitis model has been described previously." (PMID 30415390, 2019).